SPHK1 (sphingosine kinase 1)
Diseases named in the same sentence as SPHK1 in open-access papers (continued):
Sharing a sentence is not in itself a finding about the gene and the disease.
liver cancer (11 papers, 2016 to 2026). An epithelial or non-epithelial malignant neoplasm that arises from the liver. "The alteration of cell proliferation and death caused by SphK1 knockout in liver cancers could be attributed to changes of S1P, sphingosine or other sphingolipids." (PMID 29643998, 2018). "We aimed to evaluate the role of SphK1 in the development of primary liver cancer by using a mouse model of diethylnitrosamine (DEN)-induced liver cancer in the SphK1 knockout (SphK1−/−) mouse." (PMID 29643998, 2018). "We show that DEN-induced liver cancers in SphK1−/− mice were significantly less and smaller than those in wild type (WT) mice." (PMID 29643998, 2018). "When analysed at both 19 and 34 weeks post-DEN injection the number of DEN-induced macroscopic liver cancers in the SphK1−/− mice was significantly reduced by 60% compared to the numbers in the WT mice." (PMID 29643998, 2018). "Taken together, we conclude that HULC promotes tumor angiogenesis in liver cancer through miR-107/E2F1/SPHK1 signaling." (PMID 26540633, 2016). "In summary, in this study we report that HULC is able to promote the tumor angiogenesis through miR-107/E2F1/SPHK1 signaling in liver cancer." (PMID 26540633, 2016). "Similarly, analysis of publicly available H3K27ac ChIP-seq data sets comparing the SE landscapes in liver cancer cell lines to normal liver tissues identified that sphingosine kinase 1 (SPHK1) acquires an SE in liver cancer cell lines." (PMID 34109280, 2021). "Silencing of SPHK1 attenuates liver cancer xenograft tumor growth and metastasis." (PMID 34109280, 2021). "On the other hand, long non-coding RNA HULC (Hepatocellular carcinoma up-regulated long non-coding RNA) could upregulate Sphk1 and promote liver cancer angiogenesis." (PMID 28991193, 2017). "It has been reported that the mRNA levels of SPHK1 are increased in liver cancer tissues." (PMID 26540633, 2016). "Thus, we conclude that lncRNA HULC might be related to the angiogenesis in liver cancer by the up-regulation of SPHK1." (PMID 26540633, 2016). "To assess the therapeutic potential of SphK1 inhibition, we induced HCC-like liver cancer in mice with a single injection of DEN." (PMID 38200582, 2024). "Microscopic analysis of the liver cancers at 19 weeks post-DEN injection using H&E stained sections confirmed the significant reduction in the SphK1−/− mice compared to WT mice." (PMID 29643998, 2018). "Thus, SphK1 maybe a potential therapeutic target in primary liver cancer." (PMID 29643998, 2018). "Therefore, we supposed that HULC might promote angiogenesis through SPHK1 in liver cancer." (PMID 26540633, 2016). "Sphingosine kinase 1 (SPHK1) facilitates cell survival, proliferation, transformation, and angiogenesis, while miR-506 targets SPHK1 to reduce its expression at the cellular, mRNA, and protein levels, inhibiting liver cancer angiogenesis." (PMID 40248198, 2025). "SphK1 deletion significantly reduced the number and the size of DEN-induced liver cancers in mice." (PMID 29643998, 2018). "Among several key enzymes regulating the levels of ceramide, sphingosine and S1P, SphK1 but not SphK2 mRNA expression was significantly increased in DEN-induced liver cancer tissues compared with liver tissues without DEN treatment." (PMID 29643998, 2018). "Finally, we analyzed the TCGA study of human liver cancer and found that the survival of top one-third of HCC patients ranked by the SphK1 expression from the highest to lowest was statistically significantly worse than that of bottom one-third patient." (PMID 29643998, 2018).
triple-negative breast carcinoma (11 papers, 2014 to 2025). An invasive breast carcinoma which is negative for expression of estrogen receptor (ER), progesterone receptor (PR), and human epidermal growth factor receptor 2 (HER2). "A proliferative role for IGFBP-3 is observed in triple-negative breast cancer (TNBC) cells via modulating sphingosine kinase-1 (SphK1) localization to activate EGFR signaling." (PMID 39619437, 2024). "In addition to their role in proliferation and invasion, increased expression of SPHK1 also contributes to poor OS of triple-negative breast cancer patients." (PMID 36309544, 2022). "In addition, sphingosine kinase 1 (SPHK1) was overexpressed in triple-negative breast cancer and promoted metastasis via nuclear factor kappa B/sphingosine kinase 1 (NFκB/SPHK1) signaling pathway activation." (PMID 36313729, 2022). "SPHK1 is overexpressed in triple-negative breast cancer (TNBC) and promotes metastasis." (PMID 33660008, 2021). "A combination of the non-specific SphK1 inhibitor SKI-II with gefitinib significantly inhibited growth of xenograft MDA-MB-468 triple-negative breast cancer (TNBC) tumours, whereas neither SKI-II nor gefitinib alone had any effects." (PMID 31752564, 2020).
ischemia (10 papers, 2011 to 2025). A hypoperfusion of the BLOOD through an organ or tissue caused by a PATHOLOGIC CONSTRICTION or obstruction of its BLOOD VESSELS, or an absence of BLOOD CIRCULATION. "In most of these studies, inhibition of S1P signaling in ischemia was achieved by using S1P receptor gene-deficient models or the pharmacological inhibition of SphK1 and SphK2 enzymes, which made I/R injury more severe and/or reduced the benefits of ischemic pre- and post-conditioning." (PMID 32722120, 2020). "The increased expression of SphK1 also occurred in ischemia-induced neurons, and SphK1 inhibition attenuated neuroinflammation." (PMID 34737701, 2021). "To further investigate the function of SPHK1, we used the cell model of ischemia by subjecting cultured neuronal cells to oxygen and glucose deprivation/reperfusion (OGD/R)." (PMID 34051800, 2021). "In contrast, expression of Sphk1 mRNA showed a prominent increase after ischemia that was detected as early as 3 h after reperfusion, peaking at 24 h, and declining afterwards." (PMID 31165772, 2019). "In contrast, Sphk1 overexpression was sufficient to reduce the infarction size, attenuate neuroinflammation, sustain neuronal viability and prevent mitochondrial abnormalities during brain post-ischemia dysfunction." (PMID 37705748, 2023). "METTL14 promotes endothelial inflammation and atherosclerotic plaque formation by mediating m6A modification of forkhead box O1 (FOXO1), and ischemia-induced ALKBH5 facilitates endothelial angiogenesis by mediating demethylation of sphingosine kinase 1 (SPHK1)." (PMID 36830642, 2023). "Given that the kinase SphK1 is a major contributor to S1P generation in several tissues, our results showing upregulation of SphK1 mRNA after ischemia suggested that this condition might increase the cerebral concentration of S1P." (PMID 31165772, 2019). "In addition, it remains to be explored whether the activation of FoxO3/SPHK1 signaling occurs during the ischemia phase or following reperfusion." (PMID 34051800, 2021).
acute myeloid leukemia (9 papers, 2014 to 2024). Acute myeloid leukemia (AML) is a group of neoplasms arising from precursor cells committed to the myeloid cell-line differentiation. "MP-A08 is a novel sphingosine kinase 1 (SPHK1) inhibitor with activity against acute myeloid leukemia (AML)." (PMID 38399263, 2024). "The SPHK1-specific inhibitor SKI-II has also been reported to specifically inhibit the growth of human acute myeloid leukemia cells in vitro while being safe for PBMC from healthy donors." (PMID 36823149, 2023). "Furthermore, inhibitors of SphK1 have demonstrated preclinical activity in acute myeloid leukemia (AML)." (PMID 29441205, 2018). "Similarly, the sphingosine kinase 1 inhibitor MP-A08 when combined with the BH3 mimetic, Venetoclax also exerts tumor suppressive activity against Acute myeloid leukemia (AML)." (PMID 38599378, 2024). "Thus, inhibition of SPHK1 in human acute myeloid leukemia cells, but not the inhibition of SPHK2, induces MCL-1 degradation." (PMID 37020867, 2023).
asthma (9 papers, 2015 to 2023). "S1P and SPHK1 are associated with the actions of TNF-α, a cytokine critical for inflammation and autoimmune disorders, for example, inflammatory bowel disease, rheumatoid arthritis, and asthma." (PMID 28270699, 2017). "However, reduction of SphK1 expression by genetic deletion or siRNA or inhibition of activity decreased allergen-induced airway inflammation in ovalbumin sensitized and challenged murine model of asthma." (PMID 29301259, 2018).
cervical carcinoma (9 papers, 2015 to 2026). A carcinoma arising from either the exocervical squamous epithelium or the endocervical glandular epithelium. "In conclusion, we demonstrated that elevated expression of SPHK1 is significantly associated with the development and progression of cervical cancer." (PMID 26311741, 2015). "SKI-V-induced cytotoxicity in cervical cancer cells was largely inhibited by sphingosine-1-phosphate or the SphK1 activator K6PC-5, but was sensitized by adding the short-chain ceramide C6." (PMID 35541904, 2022). "Overexpression and/or overactivation of sphingosine kinase 1/2 (SphK1/2) is important for tumorigenesis and progression of cervical cancer." (PMID 35541904, 2022). "Most importantly, the overall survival rate among cervical cancer patients expressing low levels of Sphk1 is much better than among those expressing high levels of the enzyme." (PMID 27811358, 2016). "SPHK1 expression was examined in 287 formalin-fixed, paraffin-embedded cervical cancer tissues using immunohistochemistry, and its clinical implications and prognostic significance were analyzed." (PMID 26311741, 2015). "Expression of SPHK1 represents a novel and independent biomarker for the prognosis of patients with cervical cancer." (PMID 26311741, 2015). "We suggest that therapeutic targeting of SPHK1 is a potential therapeutic strategy for the treatment of cervical cancer." (PMID 26311741, 2015). "Immunohistochemical analysis revealed that expression of SPHK1 was significantly increased in cervical cancer compared with normal tissues." (PMID 26311741, 2015). "Consistent with previous reports, this study showed that the expression of SPHK1 is increased in both cervical cancer cell lines and tissues." (PMID 26311741, 2015). "We examined SPHK1 protein expression in 287 cervical cancer and 5 normal cervical tissue samples using immunohistochemical staining." (PMID 26311741, 2015). "The purpose of this study was to evaluate the clinical implications and prognostic significance of SPHK1 expression and to investigate the in vitro and in vivo effects of targeting SPHK1 with pharmacological inhibitors in cervical cancer." (PMID 26311741, 2015). "Consistent with findings from the tissue samples, SPHK1 protein was strongly expressed in all human cervical cancer cell lines examined." (PMID 26311741, 2015). "We provide the first convincing evidence that SPHK1 is involved in tumor development and progression of cervical cancer." (PMID 26311741, 2015). "Our findings indicate that inhibition of SPHK1 with pharmacological inhibitors results in potent antitumor activity in cervical cancer in vitro and in vivo." (PMID 26311741, 2015). "Taken together, our data suggest that SPHK1 is a potentially useful predictor for outcome of cervical cancer." (PMID 26311741, 2015). "We further demonstrated that blocking SPHK1 with pharmacological inhibitors significantly impaired cervical cancer cell survival and inhibited their proliferation." (PMID 26311741, 2015). "In particular, we found that SPHK1 is a novel independent biomarker for predicting RFS of patients with cervical cancer." (PMID 26311741, 2015). "We examined the relationship between SPHK1 expression in cervical cancer tissue and different clinicopathological characteristics." (PMID 26311741, 2015). "Our findings suggest that SpHK1/S1P/S1PR1 may serve as a promising target for the treatment of cervical cancer." (PMID 41513624, 2026). "Similarly, the MP6 gene set which contains S100A8/A9 downstream of SpHK1/S1P/S1PRs has the potential to serve as a predictive marker for cervical cancer response to immune checkpoint blockers." (PMID 41513624, 2026). "These evidences supported that targeting SphK1/2 could achieve significant activity against cervical cancer cells." (PMID 35541904, 2022). "Poor oncologic prognosis in association with SPHK1 expression has also been reported in cervical cancer and non-Hodgkin lymphoma." (PMID 33660008, 2021).
cervical carcinoma (continued). "For example, Sphk1-derived S1P promotes mitosis in human cervical carcinoma HeLa cells by binding to and activating S1PR5 on the extracellular side resulting in the downstream activation of intracellular phosphatidylinositol 3-kinase (PI3K)-AKT signaling pathway." (PMID 32456134, 2020). "In addition, Sphk1 expression is significantly higher in cervical cancer than in normal tissues, while Sphk1 inhibitors reduce cancer cell survival and promote apoptosis among cancer cells." (PMID 27811358, 2016). "Although SPHK1 has gained increasing prominence as an important enzyme in cancer biology, its potential as a predictive biomarker and a therapeutic target in cervical cancer remains unknown." (PMID 26311741, 2015). "Our data suggest that SPHK1 might be a potential prognostic marker and therapeutic target for the treatment of cervical cancer." (PMID 26311741, 2015). "We used two SPHK inhibitors, SKI-II and FTY720, to block the endogenous activity of SPHK1 in human cervical cancer cell lines." (PMID 26311741, 2015). "The SpHK1/S1P/S1PR1 pathway, which is modulated by glycolytic and lipid metabolic reprogramming, may serve as a potential therapeutic target for cervical cancer treatment." (PMID 41513624, 2026). "Further, SKI-V blocked SphK activation and induced ceramide accumulation in primary cervical cancer cells, without affecting SphK1/2 expression." (PMID 35541904, 2022). "However, there are no available data on the expression of SPHK1 in cervical cancer and its biological and clinical significance." (PMID 26311741, 2015).
head and neck squamous cell carcinoma (9 papers, 2014 to 2026). A squamous cell carcinoma that arises from any of the following anatomic sites: lip and oral cavity, nasal cavity, paranasal sinuses, pharynx, larynx, and salivary glands. "Sphingosine kinase 1 (SphK1) overexpressed in head and neck squamous cell carcinoma (SCC) regulates tumor growth." (PMID 29109864, 2017). "As the overall survival rates of squamous cell carcinoma of the head and neck (HNSCC) remain poor due to limitations in surgery and irradiation and chemotherapy resistance, SphK1 is an important enzyme to investigate." (PMID 25245676, 2014).
leukemia (9 papers, 2016 to 2025). A malignant (clonal) hematologic disorder, involving hematopoietic stem cells and characterized by the presence of primitive or atypical myeloid or lymphoid cells in the bone marrow and the blood. "Safingol, an SphK1 inhibitor, has entered the clinical stage for the treatment of solid tumors and leukemia." (PMID 34737701, 2021). "Over expression of SphK1 is also involved in resistance to daunorubicin and cisplatin in leukemia and colon cancer cells." (PMID 35201458, 2021). "SK1-I also reduced S1P levels and increased the expression of Cer derivatives in human leukemia U937 cells by inhibiting SphK1, which is related to the decrease of ERK1/2 and Akt signals." (PMID 34737701, 2021). "Upregulated expression of SPHK, particularly SPHK1, and increased levels of S1P have been linked with poor cancer prognosis and resistance to cytotoxic therapy agents in malignant cells from solid tumors, lymphomas, and leukemias." (PMID 29643855, 2018). "SphK1 overexpression it was reported for lymphomas and leukemias, suggesting that these blasts could catalyze S1P production." (PMID 26824863, 2016). "Selective inhibition of SphK1 by VPC96091 reduced epidermal growth factor (EGF) driven S1P levels and increased Akt/ERK phosphorylation in human leukemia U937 cells and mice model." (PMID 34737701, 2021).
renal fibrosis (9 papers, 2017 to 2025). A final common manifestation of a wide variety of chronic kidney diseases characterized by glomerulosclerosis and tubulointerstitial fibrosis. "To explore the association of pro-fibrotic factor Sphk1 with TNFSF14 pathway during renal fibrosis pathogenesis, we measured Sphk1 expression in Tnfsf14-deficient mice." (PMID 33231567, 2020). "Quercetin has been demonstrated to be efficacious in the inhibition of these deleterious processes by means of the inactivation of the SphK1-S1P (sphingosine kinase-1 and sphingosine-1-phosphate) signaling pathway, which is implicated in the pathogenesis of renal fibrosis." (PMID 40807271, 2025). "Sphk1 deficiency induced renal fibrosis to a lesser extent in diabetic mice." (PMID 33231567, 2020). "Taken together, these data suggest that SphK1 promotes renal fibrosis via TGF-β/ERK/AP-1/NF-κB/CK2α pathways and by inhibiting PP2A in oxidant-induced kidney injury." (PMID 35409370, 2022). "Taken together, these data suggest that both SphK1 and SphK2 promote renal fibrosis through different downstream signaling pathways in oxidant-induced kidney injury." (PMID 35409370, 2022). "Sphk2–/– mice develop less renal fibrosis than Sphk1–/– mice, and S1P and SphK2 are part of a corepressor complex that influences histone acetylation and gene expression; therefore we focused on identifying targets downstream of SphK2." (PMID 36267620, 2022). "Previous reports have shown that quercetin deactivated the SphK1-S1P (sphingosine kinase-1) signaling pathway, and hence inhibited the development of renal fibrosis." (PMID 36013325, 2022). "SphK1 and SphK2 differentially regulate cell proliferation and inflammation, whereas both promote renal fibrosis." (PMID 35409370, 2022). "In I/R kidney injury, renal fibrosis was similar between wild and SphK1-knockout mice, suggesting a minor role of SphK1 for I/R-induced fibrosis." (PMID 35409370, 2022). "Moreover, it is well-established that Sphk1/S1P signaling promotes renal fibrosis by up-regulating miR-21, and Sphk1 silencing by siRNA treatment results in a reduction in fibronectin." (PMID 33231567, 2020). "However, how TNFSF14 pathway correlates Sphk1 expression during renal fibrosis progression is unclear." (PMID 33231567, 2020). "All these results suggest that Sphk1 is an important factor during UUO-induced renal fibrosis." (PMID 33231567, 2020). "In contrast to the pro-fibrotic role of Sphk1, it was found that Sphk2-deficient rather than Sphk1-deficient mice were protected from folic acid or ischemia-reperfusion injury-induced renal fibrosis." (PMID 33231567, 2020). "However, it was also reported that SphK1 deficiency results in CCL2 reduction and prevention of renal fibrosis in diabetic nephropathy." (PMID 28282921, 2017). "Moreover, this is the first report showing that the TNFSF14 pathway potentiates pro-fibrotic factor Sphk1 expression, which may be the underlying mechanism of TNFSF14-mediated renal fibrosis." (PMID 33231567, 2020). "In the present study, we have provided direct evidence, for the first time, that TNFSF14 is a novel pro-fibrotic factor in renal fibrosis progression, for which TNFSF14 up-regulates Sphk1 expression." (PMID 33231567, 2020). "The discrepancy between these results may be related to the different renal fibrosis models, and the pro-fibrotic effects of Sphk1 were not obvious in acute kidney injury model." (PMID 33231567, 2020). "Additionally, berberine synergistically reduces renal fibrosis by suppressing the Notch/Snail pathway (downregulating Jagged1, Notch1, and Snail1) and the RhoA/ROCK pathway (reducing FN accumulation), as well as blocking the SphK1- S1P signaling cascade (decreasing S1P2 receptor expression)." (PMID 40567371, 2025).